ATM (ATM serine/threonine kinase)
Diseases named in the same sentence as ATM in open-access papers (continued):
Sharing a sentence is not in itself a finding about the gene and the disease.
cancer (continued). "For ATM, 537/908 (59.1%) cancers had reduced/absent expression compared to normal mucosa and for Ku70, 443/908 (48.8%) cancers had reduced/absent expression." (PMID 23154512, 2012). "Reduced ATM expression was found not only in cancer cell lines but also in non-malignant MCF10A cells during passage in culture." (PMID 23251624, 2012). "By large, the molecular biology of human and murine cancer seem to follow the same mechanistic paradigms, however, it is conceivable that ATM is an exceptional case playing a major tumor suppression role in human cancer, but not in murine cancer." (PMID 19421407, 2009). "The ATM and ATR pathway thus serves as a crucial cellular anti-cancer barrier." (PMID 18577246, 2008). "Moreover, constitutive activation of ATM and CHK2 has recently been demonstrated in a subset of malignant tumours." (PMID 17940507, 2007). "Interestingly, among several well‐established CRL5 substrates that were examined, including integrin β1, p‐SRC (Y416), ATM, RPB1, EGFR, DEPTOR, and NOXA, only integrin β1 consistently accumulated across all cancer cell lines upon APC11 knockdown using two independent siRNAs targeting APC11." (PMID 41159544, 2026). "Of the 186 patients without germline P/LP variants and available cancer genomes–exomes, 41/186 patients had a somatic variant in the DNA damage response pathway (ATRX, ATM, PPM1D, POLE) and 21/186 had a variant in the MAPK-ERK pathway (BRAF, NF1, PTPN11, MAPK12)." (PMID 40072012, 2025). "Moreover, inhibitors of PARP, ATM and ATR may be able to take advantage of DNA-repair defects in cancer to increase genomic instability." (PMID 40565309, 2025). "This pattern suggests that statins may partially inhibit cancer DNA repair mechanisms by altering the normal phosphorylation dynamics of key kinases such as CHEK2 and ATM (which also decreases their phosphorylation), thereby weakening the cellular response to DNA damage." (PMID 40832614, 2025). "This may be a reason why ATM inhibitors have not been as successful as many other DDR targeting cancer therapeutics." (PMID 38347838, 2024). "Importantly, rearrangements found in cancers overlapping transcription-replication collision sites are detected in non-transformed cells and increase following treatment with ATM and ATR inhibitors." (PMID 38773641, 2024). "Furthermore, a large subset of cancer syndromes tested here are associated with the absence of MRE11 foci or an unusual shape of MRE11 foci: this is the case of the BS, FANC, NBS, and ATM cells, in agreement with the literature." (PMID 39335159, 2024). "The association of CHEK2 mutation with metastasis appears paradigmatic but gender dependent: A pan-cancer analysis across >10 different cancer types demonstrated 1.8-fold enrichment for CHEK2 (P = 0.045), but not ATM, mutations in metastatic relative to primary tumors only in women, not in men." (PMID 37390209, 2023). "Because both the ATM and MRE11 genes, which as act as players in the MNR (MRE11/NBS1 (Nibrin)/RAD50 (RAD50 double strand break repair protein) DNA damage repair system, participate in double strand breaks (DSB) repair, their frequent splicing alterations in MSI cancers lead to impaired activity." (PMID 36833239, 2023). "However, in post-formed tumors, recent studies suggest that ATM signaling can also be advantageous to cancer cells and several cancer cells have an upregulated ATM signaling rather than a downregulated ATM signaling." (PMID 36650267, 2023).
cancer (continued). "Furthermore, treatment with the PARP inhibitor olaparib upregulates PD-L1 expression through the formation of cytotoxic DSBs and activation of ATM/ATR/Chk1 kinases in BRCA2-depleted cancer cells independent of the IFN pathway." (PMID 37174127, 2023). "Because ATM and CHK2 inhibitors are largely ineffective in cancer clinical trials, development of activators of these kinases might afford more complete cell cycle control especially in conjunction with cyclin-dependent kinase 4/6 (CDK4/6) inhibitors that have shown efficacy in the clinic." (PMID 37390209, 2023). "This may result in the activation of DDR and leads to persisted ATM signaling in malignant tumors, albeit in cancer cells ATM is no longer interconnected to cell-cycle arrest and apoptosis." (PMID 36233063, 2022). "While prevalences for ATM, BRCA1, BRCA2, and PALB2 in this study are consistent with prevalences observed in the literature, we calculated that as many as 1.22% of individuals in both cohorts unselected for personal or family history of cancer harbored GPV in CHEK2." (PMID 35805029, 2022). "In addition to serving as a biomarker, ATM and BRCA1 are potential targets for anti-cancer therapy." (PMID 34068585, 2021). "Further studies of various factors identified by our screens could facilitate successful stratification of cancer patients and/or elucidate new ATM-dependent pathways that compensate in the absence of functional ATR." (PMID 34329458, 2021). "Therefore, disrupting PARP, ATM, ATR/CHK1, WEE1, or DNA-PK activity may selectively contribute to accumulation of DNA damage in tumors, sensitize cancer cells to killing, and ultimately induce cell death." (PMID 34930377, 2021). "Notably, HMGA2 is also involved in the modulation of DNA damage response by altering the expression or phosphorylation of DNA damage checkpoint proteins including ATM and ATR/CHK1 axis, leading to the increased sensitivity to diverse genotoxic insults upon HMGA2 downmodulation in cancer cells." (PMID 34887387, 2021). "Similar to induction of replication stress, Western blot analyses also showed a time-dependent, significant increase in levels of phosphorylated Chk1 and Chk2, demonstrating strong activation of both ATR-Chk1 and ATM-Chk2 DDR signaling pathways specifically in the cancer but not noncancerous cells." (PMID 34425836, 2021). "If ATM-phosphorylated MDC1 does not require RNF8 to mediate cisplatin resistance, we anticipated that the depletion of RNF8 alone would not change the si-MDC1-induced cisplatin sensitivity in BIN1-deficient cancer cells." (PMID 34948122, 2021). "Thus, dysfunctionalities of other DDR factors involved in HR-mediated DSB repair, such as RAD51, ATR, ATM, and CHK1/2, are being studied to expand the spectrum of cancer patients that could benefit from PARP inhibitor treatments." (PMID 34363951, 2021). "Indeed, recent evidence suggest that ATM possesses non-canonical roles in promoting tumor growth and its activity is intimately associated with limited MOMP and caspase activation in cancer cells." (PMID 32566127, 2020).
cancer (continued). "Interestingly, the negative correlation of APE2 expression with ATM expression in all cancer types analyzed (excepting liver), suggests that APE2 and ATM may be in different DDR pathways." (PMID 32111912, 2020). "Our data indicates that active ATM signaling is indeed necessary for mitochondrial structural integrity in cancer cells similar to normal physiological conditions and SIRT3 stimulation does not alleviate structural changes in mitochondria in ATM deficient DLBCL cells." (PMID 33273545, 2020). "However, the relative distribution of HR mutation among subtypes were varied, though all subtypes had relatively high rates of ATM, BRCA, and POLQ mutations, with FANCM mutations common to mucinous and non-specified carcinomas." (PMID 33214570, 2020). "In addition, inhibition of DDR kinases, such as ATM and ATR, has been revealed to increase the response to ionizing radiation in some kinds of cancer including ovarian and cervical carcinoma in vitro, while was not capable of increasing the response to platinum drugs." (PMID 30975222, 2019). "Hence, ATM and the MRN complex are the major sensors or mediators in the DDR and have been considered promising targets for sensitizing cancer cells to radiation or chemotherapy; inhibiting ATM sensitized cancer cells and impaired cell migration and invasion in vitro." (PMID 31783569, 2019). "Transient suppression of PP2A activity or expression markedly improves ATM activation, restores DNA repair, inhibits apoptosis and enhances survival of stem cells without any significant effect on differentiated non-stem cells and cancer cells." (PMID 29706648, 2018). "Indeed, the correlation of ATM with CTL scores was significantly higher in cancers where neoantigen levels were not indicative of immune infiltration." (PMID 29615613, 2018). "The ATM deficiency in C9orf72-ALS patients, however, does not appear to predispose to cancer." (PMID 29584802, 2018). "While we demonstrate that this protective mechanism exists in normal untransformed fibroblasts, it is of interest to understand whether it remains active in cancer cells, particularly where ATM function is not impaired." (PMID 29294106, 2018). "Growing evidence clearly support a significant role of ATM, in addition to its master ability to control the DDR, as principle modulator of oxidative stress response and mitochondrial homeostasis, as well as in the regulation of autophagy, hypoxia, and cancer stem cell survival." (PMID 29616191, 2018). "We expect that additional medicinal chemistry efforts to optimize GSK635416A, or other ATM inhibitors, may fuel a much needed improvement in treatment options for HNSCC patients, as well as other cancer patients that respond poorly to standard chemoradiotherapy." (PMID 29088757, 2017). "In our study, however, ZnPT treatment in cultured cancer cells did not induces DNA-damage responses, as reflected by the absence of γ–H2AX foci formation and failure to increase DNA-damage response-linked phosphorylation of ATM, H2AX, Chk1 and Chk2." (PMID 28086217, 2017). "Therefore, the assay described, in which of the phosphorylation of ATM-specific targets (SMC1 and KAP1) are collectively assessed, could provide a reliable way to determine ATM function in cancer patients and guide subsequent treatment options." (PMID 27588518, 2016).
cancer (continued). "The anti-tumor effect of Rh2E2 was demonstrated by the induction of genotoxic stress on LLC-1 cancer cells, but not in normal lung fibroblasts through activation of Chk1 and ATM signaling, leading to phosphorylation of the genotoxic stress marker H2A.X, and a reduction in DNA synthesis." (PMID 26799418, 2016). "Our results identified HMGA2 as a novel negative modulator of the ATM dependent signaling pathway at telomeres and provided functional evidence for the additional telomere- and genome-protective role that cancer (stem) cells benefit from when they express HMGA2." (PMID 26799419, 2016). "We found that ATM protein expression was frequently lost or reduced in cancer cells (but not stromal cells), suggesting that IHC analysis of ATM protein expression may constitute a valuable tool to identify patients with loss of ATM function." (PMID 27602502, 2016). "More recently, regulation of oxidative stress by ATM has been proposed to play a role in several cellular functions including haematopoietic and neuronal stem cell self-renewal and survival, RTK activation and hypoxia, that are often aberrantly regulated in cancer." (PMID 24681585, 2014). "However, PARP1 inhibition and the subsequent synthetic lethality can be used on other cancers that do not have mutations in BRCA1 or BRCA2 but that have a defect in the HR pathway, including mutations in ATM, Chk2, Rad51, and NBS1." (PMID 24795863, 2014). "So far there is no report stating the activation of ATM in any MPTQ treated cancer cells." (PMID 23824039, 2013). "Recent advances showed that selenium can activate early barriers of tumorigenesis, namely senescence and DNA damage response, by rapidly activating ATM, which in turn initiates a cascade of DNA damage response and cellular senescence in non-cancerous and cancer cells." (PMID 23977169, 2013). "In addition, metformin appears to sensitize cancer cells against further DNA damages through the modulation activity of checkpoint homolog kinase 2 (CHK2), which play an important role in mediating the DNA damage response of ATM." (PMID 24958265, 2013). "The phosphorylation of ATM could activate NF-κB pathway via NEMO, which leads to the activation and expression of a variety of pro-proliferative and anti-apoptotic genes, thus protecting cancer cells from apoptosis." (PMID 23365634, 2013). "Among the ten genes, five of the TSGs (ATM, APC, BRCA2, NF1, and PTEN) were annotated with positive effects on apoptosis; the other three TSGs (PEG3, SPARC, and RPS6KA2) were also reported to increase apoptosis in sporadic epithelial OVC or other types of cancer." (PMID 22952919, 2012). "Recently, it has been shown that ATM kinase activity may exert positive or negative effects in cancer therapy pointing to the requirement for studies that further elucidate the possible connections between ATM activation and cancer markers." (PMID 24213315, 2012). "It remains to be clearly defined whether metformin's ability to strongly activate the ATM-regulated DDR checkpoint is the critical event that prevents neoplastic epithelium from progressing unimpeded into invasive cancer in individuals without type 2 diabetes." (PMID 22170748, 2011). "However, it is presently unclear whether ATM is exhibiting this deletion in the HNSCCs, because this protein has an important role in preserving genomic homeostasis in HNSCC and other types of cancers." (PMID 22414247, 2011).
cancer (continued). "Taken together, ATM-, ATR-, and NHEJ-dependent DNA damage response plays a central role in tumorigenesis and agents that disrupt this response may lead to the development of cancer." (PMID 18577246, 2008). "Moreover, inhibitors targeting different stages of the cell cycle, such as ATM inhibitors, ATR inhibitors, WEE1 inhibitors, and CHK1 inhibitors, have been developed in recent years, and their combination with PARP inhibitors has demonstrated enhanced anti-cancer efficacy." (PMID 40606759, 2025). "Interestingly, Chen and colleagues uncovered a cancer-promoting role for the ATM kinase, proving that ATM activation by oxidative stress, rather than DNA damage, drives the expression of IL-8, a pro-inflammatory cytokine that enhances cancer cell migration and invasion." (PMID 40565309, 2025). "The lack of ATM or reduction of its phosphorylated form shift the glucose-dependent energy metabolism to other substrates and cause reduction of OXPHOS and mitochondrial dysfunction, thus rendering cancer cells more sensitive to oncogene driver inhibitors and apoptotic stimuli." (PMID 37932830, 2023). "Inhibiting the ATM pathway with concomitant treatment of TMZ may act synergistically in a prolonged manner even during post-treatment, thereby serving as a more severe treatment strategy to kill or suppress the proliferation of e.g., cancer progenitor cells that are more resistant to chemotherapy." (PMID 35565340, 2022). "Thus, our study uncovers anew crosstalk between ATM and Sam68, which may represent a paradigm for the functional interaction between the DDR pathway and RNA binding proteins, and a possible actionabletarget in human cancers." (PMID 36010841, 2022). "Moreover, ATM is activated by hypoxia, and stabilizes the transcription factor HIF1α by direct phosphorylation or via the TRAF6/H2AX/HIF1α signaling axis, which could significantly increase cancer survival, invasion, and metastasis." (PMID 34070860, 2021). "The pattern of ATM activation in hypoxia, however, is not clear-cut and may depend on cancer type." (PMID 32864165, 2020). "NGS analyses with Comprehensive Cancer Panel highlighted the presence of multiple non-targetable mutations in fms-related tyrosine kinase 4 (FLT4), ubiquitin-protein ligase E3 component N-recognin 5 (UBR5), ataxia telangiectasia mutated (ATM), and TATA-box binding protein associated factor 1 (TAF1)." (PMID 30172261, 2018). "In our study, when cancer cells were exposed to drugs and ionizing radiation, low expression of XRRA1 could increase the phosphorylation of DNA repair pathway factors CHK1, CHK2, and ATM and reduce the expression of γ-H2AX, which is believed to participate in DNA repair in the nucleus." (PMID 29082250, 2017).